MMP9 (matrix metallopeptidase 9)
Diseases named in the same sentence as MMP9 in open-access papers (continued):
Sharing a sentence is not in itself a finding about the gene and the disease.
COVID-19 (continued). "Specifically, in COVID-19, these genes were CD52, ISG15, and MMP9; in influenza, they included IFI44L, IFIT3, ISG15, and OAS1; and in HIV, OAS1 was identified." (PMID 38601162, 2024). "In line with all these authors, we observed higher plasma levels of MMP-9 and TIMP-1 in COVID-19 patients who developed ARDS." (PMID 37509076, 2023). "In particular, the upregulation of MPO, MMP9, TLR2, and LCN2 in the lungs of sepsis-induced ARDS mice suggests their crucial role in developing lung injury in COVID-19 and sepsis." (PMID 37822934, 2023). "Some studies further suggested that COVID-19 patients have chronically elevated levels of neuroinflammatory factors such as blood GFAP and MMP-9." (PMID 38058998, 2023). "The severe form of COVID-19 has many similar features to sepsis, and both MMP-2 and MMP-9 have been considered potential biomarkers for septic patients." (PMID 37509076, 2023). "On hospital admission, COVID-19 patients showed significantly higher plasma levels of MMP-9 and TIMP-1 as well as a higher MMP-9/TIMP-1 ratio compared to HD (p < 0.0001, p < 0.0001 and p = 0.0299, respectively) (respectively)." (PMID 37509076, 2023). "Regarding zymography data, on the hospital admission of COVID-19 patients with a higher plasma activity, MMP-2 and MMP-9, compared to HD, were observed (p < 0.0001 and p < 0.0001, respectively) (respectively)." (PMID 37509076, 2023). "Finally, among the 15 COVID-19 patients with severe NS on hospital admission requiring PL for diagnostic purposes, an investigation of neuronal and astrocyte damage (NfL and GFAP), myeloid activation (sCD163) and BBB alteration biomarkers (MMP-9 and TIMP-1) on CSF samples was performed." (PMID 37759493, 2023). "Using next-generation ELISA, the plasma levels of MMP-9 and TIMP-1 were evaluated in 129 COVID-19 patients and 53 HD." (PMID 37509076, 2023). "Serum level of MMP9 is found to be significantly elevated in the more severe cases of COVID-19 and in combination with brain-derived neurotrophic factor (BDNF), MMP9 has shown potential as a predictive marker for COVID-19 severity." (PMID 36768847, 2023). "Increased activities of matrix metalloproteinase 9 (MMP-9), as well as matrix metalloproteinase 8 (MMP-8), were reported in patients with severe form of COVID-19 8,9." (PMID 36438922, 2022). "Searching for a marker that would improve and simplify the ranking in COVID-19, the study intended to evaluate the relationship of MMP-9 with VEGF A, BDNF, and MMP-8 with the COVID-19 severity." (PMID 36438922, 2022). "The study investigated the relationships between clinical, biochemical parameters and active tissue mediators (MMP-9, MMP-8, BDNF, and VEGF A), that predominate during COVID-19, depending on the stage of the disease." (PMID 36438922, 2022). "Studies utilizing cultured endothelial cells treated with COVID-19 patient plasma in vitro showed similar changes in HA, as well as hyaluronidase, MMP2, MMP9, and cathepsin activity." (PMID 35872762, 2022). "For example, MMP-9 and its MMP-9/NGAL heterodimer were significantly increased in the plasma of COVID-19 patients compared to healthy controls." (PMID 35563537, 2022). "Several enzymes can be used as a target for COVID-19 therapeutics including PI3K ̧ mTOR, growth factor receptor, RAF, MAP2K2, FLT3, AXL, AKT, and matrix metalloprotease MMP2 and MMP9." (PMID 35251015, 2022). "Considering the interrelation of MMP-9 and BDNF, to our knowledge, for the first time, we analysed MMP-9/BDNF ratio in the COVID-19, in order to link these mediators with stages of disease development." (PMID 36438922, 2022). "The IHC analysis showed increased expression of caspase-1, ICAM-1, IL-1β, IL-6, MMP-9, TNF-α, and other markers in the hearts of COVID-19 patients." (PMID 34804033, 2021). "MMP8, MMP9, and S100A12, three genes that we found significantly upregulated in COVID-19 patient, are also common components in NETs, which further demonstrates the vital roles of NETs in COVID-19 development." (PMID 34457122, 2021).
COVID-19 (continued). "For example, the increase in IL-2, MMP9, and VEGFA is related to the mortality of COVID-19 patients." (PMID 34803696, 2021). "No statistical difference was observed in the tissue expression of AKT-1, Cav-1, MMP-9, Sphingosine-1, and TGF-β1 when testing COVID-19 and H1N1 groups." (PMID 35008594, 2021). "MMP-9 and VEGF-A were significantly elevated during the acute phase in these COVID-19 patients compared with healthy control subjects." (PMID 34853380, 2021). "There was also a significant increase observed in the immunoexpression of tissue biomarkers ACE-2, AKT-1, CD44v6, IL-4, MMP-9, α-SMA, Sphingosine-1, and TGF-β1 in the COVID-19 group." (PMID 35008594, 2021). "Increased levels of MMP-9, combined with our finding of TIMP-2 levels within normal limits throughout the observation period, suggest enhanced MMP-9 activity in these COVID-19 patients." (PMID 34853380, 2021). "After adjusting for age, COVID-19 patients with delirium had significantly higher GFAP levels at day 3 [270.5 (148.0,375.0) pg/ml vs. 113.0 (70.9,196.0) pg/ml, p = 0.021] and higher MMP-9 levels [50.3 (43.1,13.2) μg/ml vs. 28.9 (17.9,47.9) μg/ml, p = 0.003] at hospital discharge." (PMID 39352661, 2025). "For example, MMP9 upregulation has been documented in rheumatoid arthritis, while increased MMP2/9 expression facilitates resolution of pulmonary inflammation and fibrosis in patients with COVID-19." (PMID 40646747, 2025). "Coul-SR energies were generally lower in COVID-19 vs. healthy groups for both MMP7 and MMP9." (PMID 38803919, 2024). "Increased plasma levels of MMP-9 were found in patients with severe ARDS43 and COVID-19 patients." (PMID 38243064, 2024). "MMP9-FasL (COVID-19) showed the most negative (lowest) Coul-SR (−863.6) and overall SR energies (−1317.9) compared to all other groups." (PMID 38803919, 2024). "Studies on COVID-19 patients have highlighted critical brain injury biomarkers, such as neurofilament light chain (NfL), glial fibrillary acidic protein (GFAP), and matrix metalloproteinase-9 (MMP-9), which are essential in understanding the extent of neural damage." (PMID 39064167, 2024). "Finally, an investigation of neuronal (NfL) and astrocyte damage (GFAP), myeloid activation (sCD163) and BBB permeability (MMP-9 and TIMP-1) was performed on the CSF samples of hospitalized COVID-19 patients with severe NS on hospital admission." (PMID 37759493, 2023). "As for the modifications we found in MMP-2 and the absence of alterations in MMP-9, it is well known that COVID-19 predominantly affected the respiratory tract leading to acute lung failure as the most severe outcome." (PMID 36831321, 2023). "Although serum levels of MMP-3 increased after one week of hospitalization, expression levels of MMP-9 did not change with advancing disease stages, despite being higher in those affected by COVID-19." (PMID 37372128, 2023). "Previous COVID-19 findings showed elevated MMP-2 and MMP-9 levels in hospitalized patients." (PMID 36831321, 2023). "Compared with the HC group, increased serum levels of MMP-9 and IL-6 were found in COVID-19 patients regardless of the disease severity." (PMID 36139764, 2022). "We observed that TAF samples from COVID-19 and non-COVID-19 individuals expressed high levels of pro-MMP-9 and pro-MMP-2 by zymogram." (PMID 35625532, 2022). "Moreover, in TNF-α activated monocytes, ITF3756 reduces the expression of additional biomarkers of severe COVID-19, such as PTX3, ICAM-1, S100A12, PD-L1 and MMP9, further supporting a potential role for this molecule in the treatment of the disease." (PMID 35592335, 2022). "Indeed, epithelial cells from bronchoalveolar lavage fluid (BALF) on severe COVID-19 showed elevated frequencies of MMP-7+ and MMP-9+ and a tendency to increase portions of MMP-2+ and MMP-13+ compared to mild cases." (PMID 35625532, 2022). "Our data indicate that the release of MMP9 during COVID-19 is not an early event in WHO 3 subgroup (n = 18), as compared with the controls." (PMID 35075175, 2022).
COVID-19 (continued). "In conclusion, serum MMP3 may help to early predict the severity of COVID-19 and both proteins, MMP3 and MMP9, may contribute to define severe COVID-19 patients that may benefit from a targeted therapy on MMPs." (PMID 35075175, 2022). "Recent human COVID-19 autopsy and transplant lung studies identified abundant interstitial pro-fibrotic monocyte-derived macrophages characterized by increased expression of SPP1, MMP9, and CTSZ." (PMID 35857635, 2022). "The zymographic analysis of CSF samples from neuro-COVID-19 patients evidenced on the gel two main lysis bands, present at different levels, with an apparent molecular mass of 72 and 92 kDa, corresponding to MMP-2 and MMP-9, respectively." (PMID 36010557, 2022). "During the period of COVID-19, HLJDD was also found to play a therapeutic role in COVID-19 through regulating multiple signaling pathways based on targeting genes such as IL6, IL10, MMP9, NOS2, VEGF, and TGFβ1." (PMID 35127697, 2021). "In addition, in patients with severe COVID-19, increased concentrations of neutrophil elastase, gelatinolytic activity, and TIMP-1/MMP-9 complexes were found." (PMID 34829883, 2021). "The results suggested that the upregulation of MMP9 and TLR6 by Spike were mainly occured in THP-1 cells, which consisted with our GO analysis that myeloid cells, which contain monocytic cells were activated in COVID-19 patients." (PMID 33679778, 2021). "The COVID-19 samples presented statistically increased tissue immunoexpression of ACE-2 (p < 0.0001), AKT-1 (p = 0.022), CD44v6 (p < 0.0001), IL-4 (p < 0.0001), MMP-9 (p = 0.004), α-SMA (p < 0.0001), Sphingosine-1 (p < 0.0001), and TGF-β1 (p = 0.0315) when compared to the CONTROL group." (PMID 35008594, 2021). "MMP9 is related to neutrophil-mediated immune-inflammation, which acts as a membrane receptor for SARS-CoV-2, and, therefore, its ability to block this protein justifies the recommendation of melatonin for the treatment of COVID-19." (PMID 35723382, 2021). "Among various inflammatory markers, MMP-9 has been strongly associated with the PO2/FiO2 ratio and can distinguish between COVID-19 patients with and without respiratory failure." (PMID 34440210, 2021). "A study in Norway investigated correlations between respiratory failure and MMP-9 in 21 COVID-19 patients with respiratory failure in comparison with seven COVID-19 patients without respiratory failure." (PMID 33142828, 2020). "Assessing the course of MMP-9 values over time against respiratory failure showed that significantly high values of MMP-9 in the first two samples (days 0–2 and 3–5) could be an early indicator of respiratory failure in COVID-19 patients." (PMID 37545954, 2023). "It appears partly reasonable with our results from proteomics reanalysis, which showed a significant increase in detection of MMP-2, MMP-7, MMP-8, and MMP-14, but not the expression of the MMP-9 protein, in lung tissue from COVID-19 compared to non-COVID-19 subjects." (PMID 35625532, 2022). "Another report showed that the plasma MMP-2 levels decreased while MMP-9 levels increased in severe COVID-19 patients, but the COVID-19 non-survivors had higher MMP-2 levels than COVID-19 survivors, which is considered to be related to the activation of the renin–angiotensin system." (PMID 35741101, 2022). "Searching for a marker that could improve and simplify the estimation of COVID-19 progress and considering the predictive potency of MMP-9, the study intended to evaluate the relationship of MMP-9 with VEGF A, BDNF, and MMP-8, concerning the development, severity of disease and outcomes of COVID-19." (PMID 36438922, 2022). "To further determine whether 6 key target genes identified in this study (AKT1, MMP9, ICAM1, TLR4, BCL2, and HIF1A) could be used as therapeutic targets for sepsis and COVID-19, we downloaded the gene expression profiles of sepsis and COVID-19 patients from the GEO database (GSE95233, GSE171110)." (PMID 41411324, 2025).
COVID-19 (continued). "In COVID-19 patients experiencing delirium, levels of GFAP and MMP-9 were significantly higher compared to those without delirium." (PMID 39352661, 2025). "We found significant differences due to COVID-19 disease severity for both BDNF and NFL but not for NGF in the ratios with MMP-2 or MMP-9." (PMID 36831321, 2023). "While, serum MMP9 did not change with the progression of the WHO stage, although it was significantly higher in COVID-19 patients than in controls." (PMID 35075175, 2022). "An exception was a negative correlation between MMP-9/BDNF with IL-10/IL-17 in moderately ill and a highly positive correlation of this ratio with MMP-8 in mild, moderate, and critically COVID-19 groups." (PMID 36438922, 2022). "Indeed, pro-MMP-2 and pro-MMP-9 were present in all TAF samples from non-COVID-19 and COVID-19 patients." (PMID 35625532, 2022). "Regardless of the unchanged values of BDNF in different phases of COVID-19, we found a positive correlation between BDNF and MMP-9, MMP-8, and VEGF A, as well as a strong negative correlation of BDNF with IL-10 and cytokines ratios IL-10/IL-1, IL-10/IL-6, IL-10/IL-17, and IL-10/TNF-α." (PMID 36438922, 2022). "Investigations have found MMP-9 in several cell types of the lung, such as alveolar macrophages, airway epithelium, and in neutrophils recruited to the lung during inflammatory processes, but the major cellular sources of circulating MMP-9 in COVID-19 patients are still not evident." (PMID 34853380, 2021). "Additionally, plasma hyaluronidase activity was higher in the ICU COVID-19 patients vs. the non-ICU patients, and plasma MMP2, MMP9 and cathepsin D activities (enzymes which may cleave GAG-anchoring proteins) were significantly increased in COVID-19 patients vs. healthy controls." (PMID 35872762, 2022).
Sepsis (133 papers, 2003 to 2026). Sepsis is defined as life-threatening organ dysfunction caused by a dysregulated host response to infection. "Comparative genomic analysis identifies LTF and MMP9 as key overlapping genes implicated in both pediatric sepsis and relapsed B-ALL." (PMID 41007866, 2025). "All AUC values exceeded 0.7, indicating that LTF and MMP9 had significant diagnostic value for both pediatric sepsis and relapsed B-ALL." (PMID 41007866, 2025). "While our study identifies a novel role for MMP9 in sepsis-associated T cell exhaustion, several limitations must be considered." (PMID 41306770, 2025). "Prior studies have consistently linked elevated syndecan-1 and MMP-9 levels to adverse outcomes and multi-organ dysfunction in sepsis." (PMID 40766307, 2025). "IL-6 and MMP-9 expression activate host defense mechanisms, which have been linked to increased inflammation and vascular permeability and serve as sepsis biomarkers." (PMID 40565223, 2025). "A single-nucleotide polymorphism (SNP) at position-1562 (C/T) in the MMP-9 gene has been associated with differential MMP-9 expression and increased mortality in sepsis patients." (PMID 37622890, 2023). "In this study, we identified 8 senescence-related genes (IGFBP7, GMFG, IL10, IL18, ETS2, HGF, CD55, and MMP9) and developed a diagnostic model for the prediction of sepsis occurrence." (PMID 38259686, 2023). "This work provides clear evidence that MMP-9 is a useful biomarker in the detection of sepsis and presents a simple low-cost diagnostic tool that can be exploited to detect other sepsis biomarkers in the future." (PMID 37622890, 2023). "GEO database analysis revealed that high expression of MMP9 at the transcriptional and protein levels was associated with sepsis and venous thrombosis, consistent with the literature." (PMID 38029239, 2023). "In humans, increased MMP-9 has been associated with inflammatory bowel disease, sepsis, and exposure to pancreatic trypsin, as occurs in intestinal ischemia and reperfusion injury." (PMID 36670767, 2023). "The tissue inhibitor of matrix metalloproteinase-1 (TIMP-1) and MMP-9 can be used as potential diagnostic biomarkers for sepsis-associated AKI in clinical assessment." (PMID 36177176, 2022). "MMP-9, TIMP-1, and MMP-9/TIMP ratio were good diagnostic or prognostic biomarkers of sepsis after major abdominal surgery and were linked to sepsis-associated organ dysfunction in rats and humans." (PMID 33488296, 2021). "In conclusion, MMP-9 was found to be a biomarker of high diagnostic value for sepsis and endotoxemia in equine colic." (PMID 33488296, 2021). "Our results demonstrated that intrapulmonary knockdown of MMP-9 significantly aggravated sepsis-associated ALI as indicated by increased pulmonary edema, inflammation, oxidative stress, and lung injury score." (PMID 33628393, 2021). "An association of sepsis-related mortality disease with TIMP-1/MMP-9 ratios was found in several studies for adults and children." (PMID 33488296, 2021). "It was found that pulmonary knockdown of MMP-9 significantly increased mortality of sepsis and exacerbated sepsis-associated acute lung injury." (PMID 33628393, 2021). "In this study, only MMP-9 was found to be a biomarker of high diagnostic value for sepsis and endotoxemia in equine colic." (PMID 33488296, 2021). "They concluded that a higher TIMP-1/MMP‐9 ratio was associated with severity, coagulation state, circulating cytokine levels and mortality and proposed it as an outcome biomarker of sepsis." (PMID 31932967, 2021). "MMP-9-mediated RAGE shedding limited the severity of sepsis-associated pulmonary edema, inflammation, oxidative stress, and lung injury by suppressing the RAGE/NF-κB signaling pathway via the decoy receptor activities of sRAGE." (PMID 33628393, 2021).